MDM2 (MDM2 proto-oncogene)
Diseases named in the same sentence as MDM2 in open-access papers (continued):
Sharing a sentence is not in itself a finding about the gene and the disease.
tumor (continued). "The same study described that Mdm2+/- tumors had a decreased level of p19Arf (Cdkn2a), another tumor suppressor that is reciprocally regulated by N-myc." (PMID 33585251, 2020). "In tumor xenograft models, treatment with AMG 232 resulted in tumor growth inhibition and caused regression of MDM2-amplified tumors through the induction of growth arrest and apoptosis." (PMID 31359240, 2020). "MDM2 was found to be overexpressed in many tumor types via several mechanism including gene amplification or enhanced transcription." (PMID 32971841, 2020). "The second tumor harboring a MDM2 amplification had high‐grade morphology, polysomy of JAZF1, PHF1, and YWHAE but no rearrangements were reported, leading to a diagnosis of UUS." (PMID 32352245, 2020). "Subsequently, we demonstrated that circSERPINA3 executed its tumor oncogenic activity through sponging miR-944 and regulating the expression of MDM2." (PMID 32328195, 2020).
tumor (continued). "Amplifications of EGFR and gain of chromosomes 19 and 20 were strongly prevalent in RTK II, and PDGFRA, CDK4 and MDM2 or MDM4 amplifications were more frequent in RTK I tumours." (PMID 33339831, 2020). "MDM2 and TAB1 expression levels were associated with histological grading, whereas MDM2 and MDMX expression levels were associated with tumor size." (PMID 31892970, 2020). "Specific inhibition of MDM2 in T-cell resistant tumor cells with high MDM2 expression decreases IL-6 expression and enhances T-cell-mediated killing regardless of changes in PD-L1 expression of the tumor cells." (PMID 32655895, 2020).
tumor (continued). "Another study proved that the combination treatment of EGFR-TKIs and MDM2 inhibitors can inhibit the proliferation of tumor cells and enhance the anti-tumor effect of EGFR-TKIs." (PMID 32611363, 2020). "Our data provide the first in vivo evidence that inhibition of MAPK signaling can augment anti-tumor activity of a MDM2 antagonist in human tumor models." (PMID 32806555, 2020). "The same study also showed that the MDM2 inhibitor in syngeneic models enhanced anti-tumor immunity in the tumor microenvironment via T-cell proliferation, enhanced CD4 + T-cell activation and increased M1 macrophages." (PMID 32655895, 2020). "An early report of 47 iCCA patients showed that MDM2 overexpression correlated with the Ki-67 labeling index (p < 0.03), presence of metastases (p < 0.01) and advanced tumor stage (p < 0.05)." (PMID 33113997, 2020). "Recent studies showed that HDAC inhibitors cooperated with MDM2 inhibitors to suppress the proliferation of tumor cells." (PMID 32477121, 2020). "In our series, the immunohistochemical analyses performed on the first case of atypical lipomatous tumor stained positive for MDM2 and CDK4." (PMID 31282548, 2020). "OVTOKO and OVMANA MDM2-siRNA tumor cells compared to tumor cells alone had a dead/live tumor cell ratio of 8.8:1 (P = 0.03) and 7.7:1 (P = 0.03), respectively." (PMID 32655895, 2020). "E.g., patient tumor T16 displayed intratumor genetic heterogeneity, where differences in gene amplicons for EGFR and MDM2 were detected in different tissue fragments dissected from the tumor core." (PMID 33009951, 2020). "In a large study of 102,878 patients with different malignancies, NGS of tumor tissue revealed MDM2 amplification in 3.5% of cases." (PMID 32110946, 2020). "Agents have been developed to directly reactivate tumour suppressors or target-related molecules, such as MDM2, CDK4/6 and TGF-β." (PMID 33008426, 2020). "Mdm2 is considered a potent tumor promoter in numerous cancers and it has been highly associated with metastasis." (PMID 33114139, 2020). "Selection experiments for the tumor‐relevant proteins MDM2 and TEAD4 yielded MDM2 binders and a novel class of TEAD‐YAP interaction inhibitors that perturbed the expression of a gene under the control of these Hippo pathway effectors." (PMID 32537835, 2020).
tumor (continued). "It has been known that 20(S)-25-OCH3-PPD can destabilize MDM2 protein by promoting its ubiquitination and thereby inhibit the tumor growth." (PMID 32425780, 2020). "Hyperprogression occurred more often in case of MDM2/4 or EGFR amplification or <1% PD-L1 positive tumor cells." (PMID 32110946, 2020). "MDM2 is often amplified/overexpressed in human tumors, especially in soft tissue cancers, where its elevated levels correlate with both tumor grade and poor prognosis." (PMID 32560247, 2020). "MDM2 zinc-finger mutants, however, can escape inhibition to play important roles in tumor progression." (PMID 33149122, 2020). "Using tumor cells alone as an internal control, silencing MDM2 in both cell lines showed a significant increase in dead/live tumor cell ratio after 12 h of T-cell co-culture." (PMID 32655895, 2020). "MDM2, as an important hub for cell survival, growth, invasion, and DNA repair, remains a major therapeutic target in this tumor type." (PMID 32630235, 2020). "Ultimately, it is unlikely that cleavage of MDM2 represents the sole mechanism of tumor suppression by caspase-2." (PMID 33425918, 2020). "In a murine DDLPS xenograft model, romidepsin reduced tumor growth and lowered tumor MDM2 expression." (PMID 31620242, 2019).
tumor (continued). "MDM2 promotes BC circulating tumor cells (CTCs) and down-regulation of MDM2 in an orthotopic mouse model shows reduced CTCs and significantly increases levels of E-cadherin." (PMID 31489110, 2019). "In the ERα+ context for T47D cells, metastasis outcomes did not occur at the endpoints we tested, but we were able to ask how MDM2 expression influenced the tumor volume." (PMID 30642351, 2019). "Shaomeng Wang (University of Michigan) described MDM2 degraders that can achieve complete tumor repression and greatly improve survival of animals in leukemia models." (PMID 31408158, 2019). "We tested the role of MDM2 or MDMX knockdown in the metastatic TNBC MDA-MB-231 cells by assessing the tumor volumes and the number of endpoint CTCs." (PMID 30642351, 2019). "MDM2 overexpression can promote EMT process in tumor cells to achieve chemotherapeutic drug resistance." (PMID 31440117, 2019). "MDM2 overexpression in mice elicits tumor formation, bringing irrefutable evidence that MDM2 promotes cancer development." (PMID 31921839, 2019). "Fluorescence in situ hybridization (FISH) using MDM2/CEP12 probe set was subsequently performed and 88.3% of 60 tumor nuclei scored showed amplification of the MDM2 gene at 12q15." (PMID 31280066, 2019). "A mouse model study showed that MDM2 promotes early-stage metastasis in TNBCs, providing the first in vivo evidence for a role of MDM2 in promoting circulating tumor cells (CTCs)." (PMID 30642351, 2019). "The rhein-derived compound AQ-101 represents a potentially new, safe anti-tumor drug providing a novel strategy for targeting MDM2." (PMID 30674340, 2019). "Significant depletion of MDM2 in the tumor tissue was detected, and we also detected an increase in MDMX protein (lanes 4, 5, and 6)." (PMID 30642351, 2019). "Experimental evaluation of toxicity of MDM2 inhibitors obtained in mouse models suggests that tumor-suppressing doses of nutlin3a, RITA, MI-219, and stapled peptide ATSP-7041 do not cause weight loss and are well tolerated." (PMID 31310659, 2019). "Peak MIC‐1 plasma and tumour levels observed at 6 h post‐treatment are consistent with the peak MDM2 and p21 induction observed by protein analysis." (PMID 30536898, 2019).